ACSL3 (acyl-CoA synthetase long chain family member 3)
Diseases named in the same sentence as ACSL3 in open-access papers (continued):
Sharing a sentence is not in itself a finding about the gene and the disease.
cancer (continued). "Independent knockdown of ACSL1, ACSL3, or ACSL4 decreased cell proliferation and anchorage‐independent growth in many cancer cells and xenograft tumor growth in nude mice." (PMID 33030783, 2020). "ACSL3 and ACSL4 expression levels have been reported to be frequently altered in cancer but here we provide evidence that they have also an altered expression profile in senescence induced by oncogenic H-Ras." (PMID 30413053, 2018). "Furthermore, we examined the expression of several key ferroptosis-related proteins in radioresistant cancer cells, including GPX4, SLC7A11, Nrf2, TfR1, and ACSL3." (PMID 40102409, 2025). "To further investigate whether OA inhibits ferroptosis through ACSL3, we evaluated the effect of OA pretreatment on the erastin (or RSL3)-induced ferroptosis in ACSL3-KO cancer cells and their parental cells." (PMID 40102409, 2025). "Notably, we also found that ACSL3 knockdown and imidazole ketone erastin (IKE, an inducer of ferroptosis) synergistically restored the sensitivity of radioresistant cancer cells to radiation both in vitro and in vivo." (PMID 40102409, 2025). "In addition to ACSL1, ACSL4, and ACSL5, ACSL3 and ACSL6 also contribute to cancer progression, with their roles to be further elaborated in the context of specific cancers." (PMID 41288931, 2025). "The incorporation of exogenous MUFAs into cellular phospholipids by long chain acyl-CoA synthetase 3 (ACSL3) has been shown to be necessary for the acquisition of a ferroptosis-resistant state in cancer cells, and this process was independent of LD formation." (PMID 36776554, 2023). "The dysregulation of ACSL3 and ACSL4, which belong to the five isoforms of ACSLs, plays a key role in cancer initiation, development, metastasis, and tumor immunity and may provide several possible therapeutic strategies." (PMID 36497375, 2022). "Targeting the molecular mechanisms of ACSL3 and ACSL4 may provide more therapies for cancer treatments." (PMID 36497375, 2022). "Several ACSLs-related reviews have summarized the mechanisms and function of the ACSLs in cancer: ACSL1 and ACSL3 may lead to cancer progression and worse prognosis, while ASCL5 and ACSL6 act as key suppressor with the opposite effect." (PMID 36507355, 2022). "Future and ongoing efforts in our lab are focused on understanding whether and how ACSL3 protects KMLC cells from ferroptosis in preclinical models and how it reshapes the lipid composition in this type of cancer." (PMID 35912247, 2022). "Indeed, ablation of ACSL3 impairs in vivo tumorigenesis in KMLC mice by disrupting lipid beta-oxidation and fat composition of cancer cells." (PMID 35912247, 2022). "In our prognostic model of LUAD, we surprisingly found that ACSL3 and CISD1 were promoters of ferroptosis, whereas the remaining three genes were suppressors of ferroptosis, which was opposite of the results acquired in other cancers." (PMID 34115610, 2021). "To assess whether LPIAT1 requires ACSL3-derived substrates to control cancer cell proliferation, we overexpressed LPIAT1 with a lentiviral construct in A549 and H358 cell lines and performed cell proliferation assays upon ACSL3 knockdown." (PMID 32034305, 2020). "We previously found that the acyl–coenzyme A (CoA) synthetase long-chain family member 3 (ACSL3) is necessary for the extracellular lipid utilization and proliferation of KRAS-driven cancer cells because of its role in activation of extracellularly derived long-chain fatty acids." (PMID 33127675, 2020). "Thus, our data indicate that ACSL3 and LPIAT1 regulate cancer cell proliferation, at least in part, by acting on the same metabolic axis." (PMID 32034305, 2020). "Given the emerging importance of ACSL3 and ACSL4 in cancer, we describe here a series of subcellular fractionation experiments aimed at elucidating and comparing the subcellular distributions of these enzymes in cancer cells." (PMID 29450800, 2018).
cancer (continued). "Importantly, we show that the known fusion partners, including the novel ACSL3:ETV1 fusion gene, only account for 39% of cancers with an ETV1 rearrangement and it is therefore likely that many new partner genes remain to be identified." (PMID 18594527, 2008). "Therefore, cancer cells can be theoretically sensitized to ferroptosis by modulating the activities of enzymes involved in MUFA-PL synthesis, such as stearoyl-CoA desaturase 1 and long-chain acyl-coenzyme A synthetase-3 (ACSL3)." (PMID 40102409, 2025). "We found only 4 significant results in this analysis: First, low ACSL3 expression in Naïve B cells, and low ACSL5 and ACSL6 in Naïve CD8 cells, correlated with worse patient survival outcomes, demonstrating a potential reliance on these for an effective anti‐cancer immune response." (PMID 39853696, 2025). "In general, cancer cells are frequently confronted with energy stress due to their rapid growth and limited oxygen supply, which inhibits the activity of mTOR signaling and potentially weakens the regulatory role of the BRD4-SRPK2-SRSF2 axis on ACSL3 expression." (PMID 37993451, 2023). "Thus, targeting ACSL3 and FAO metabolic pathways might be exploited for therapeutic gain for CRC and other FAs-dependent cancers." (PMID 35414781, 2022). "ACSL3 mediates the epithelial mesenchymal transition (EMT) and metastasis of CRC cells by activation of FAO pathway to produce ATP and reduced nicotinamide adenine dinucleotide phosphate (NADPH), which sustain redox homeostasis and fuel cancer cells for invasion and distal metastasis." (PMID 35414781, 2022). "Thus, targeting ACSL3 and FAO metabolic pathways might be exploited for therapeutic gain for CRC and other FAs- addicted cancers." (PMID 35414781, 2022). "Interestingly, although the overexpression of LPIAT1 enhanced cancer cell proliferation, this effect was completely abolished upon ACSL3 knockdown, thus strongly suggesting that LPIAT1 requires ACSL3-derived arachidonyl-CoA to promote cancer cell proliferation." (PMID 32034305, 2020). "Validation of the whole-body mouse knockout of some isoenzymes such as ACSL3, ACSL5 and ACSL6 does not result in lethality or any overt dysfunction which renders them cancer cell specific vulnerabilities." (PMID 31344914, 2019).
tumor (58 papers, 2018 to 2026). "We revealed for the first time the relationships between radioresistance and FAs, ACSL3, and ferroptosis, and elucidated the underlying mechanism through which MUFAs modulate radioresistance in tumor cells." (PMID 40102409, 2025). "ACSL5 expression was inversely associated with Ki67 in low-grade tumours, while ACSL3 was positively associated with Ki67 in high-grade tumours." (PMID 41154605, 2025). "The alterations of ACAT1 and ACSL3 are closely linked to the immune tumor microenvironment and progression of LUAD." (PMID 39323079, 2024). "This is additionally corroborated by a Kras-driven mouse model of lung tumorigenesis where the loss of Acsl3 suppressed the tumor onset." (PMID 31344914, 2019). "Importantly, genetic or pharmacologic suppression of ACSL3 is cytotoxic to ccRCC cells in vitro and causes a reduction of tumor weight in an orthotopic mouse model." (PMID 36192773, 2022). "All these data allow us to hypothesize that, in NSCLC, ACSL3 overexpression is defining a metabolic scenario, associated with increased fatty acids activation conducting to an aggressive and invasive tumor cell and consequently with poor patient survival." (PMID 33030783, 2020). "In addition to ACSL3, it could be some other genes implicated in the mechanisms of response of tumor cells to statins." (PMID 33030783, 2020). "Therefore, we investigated whether the reduced PDAC progression and fibrosis, upon Acsl3 knockout, was associated with changes in tumor immune cell infiltration." (PMID 33127675, 2020). "ACSL4 expression was significantly higher in HCC than in all other tumour types, while ACSL3 expression was similar in HCC and hepatic metastases." (PMID 41154605, 2025). "Elevated ACSL3 expression initially inhibits tumor proliferation by increasing LD storage, thereby reducing FAO and cellular energy production." (PMID 41288931, 2025). "For instance, acyl-coenzyme A synthetase long-chain family member 3 (ACSL3) is markedly upregulated in disseminated tumor cells (DTCs), enabling them to evade chemotherapy and adopt a dormant phenotype." (PMID 40977686, 2025). "Mechanistically, this circRNA hijacks the miR-223-3p/ACSL3 axis to amplify lipid synthesis—ACSL3 catalyzes fatty acyl-CoA esterification, fueling triglyceride and cholesterol biogenesis—while correlating with aggressive tumor dimensions." (PMID 40722703, 2025). "ACSL3, in contrast, modulates tumor malignancy through the tumor microenvironment by regulating immune cell abundance." (PMID 41288931, 2025). "A recent study demonstrated that ACSL3 knockdown enhances the efficacy of immunotherapy in vivo and promotes the development of an anti-tumor immune microenvironment." (PMID 41288931, 2025). "Acyl-CoA synthetase long-chain family member 3 (ACSL3) regulates the accumulation of lipid droplets in ccRCC and is essential for tumor growth." (PMID 38095762, 2024). "Tumor cells enhance their capacity to metabolize fatty acids and develop a protective layer of oleic acid molecules on their surface through the action of ACSL3, enabling them to adapt to a lipid-rich environment in the lymph nodes." (PMID 38292937, 2024). "In nude mice, ACSL3 can promote tumor growth, and high expression of ACSL3 in PCa patients also predicts poorer prognosis." (PMID 37061523, 2023). "The results indicated that ACSL3, ADH1B, ALDH2, and HADHA had strongly associated with the tumor grade." (PMID 37540213, 2023).
tumor (continued). "Consistent with our previous in vitro results, ccRCC cells with ACSL3 silenced by transduction with shRNA displayed reduced growth in this orthotopic murine tumor model." (PMID 36192773, 2022). "An important factor that determines tumor cell survival is the close interaction between ACSL3, ACSL4, and ferroptosis." (PMID 36497375, 2022). "ACSL3 inhibition accordingly also reduced tumor growth in an orthotopic mouse model, indicating that this pathway is also vital for cell viability in vivo." (PMID 36192773, 2022). "Compared with the corresponding non-tumor colorectal tissues, a significant up-regulation of ACSL3 expression was detected in the CRC specimens." (PMID 35414781, 2022). "ACSL3 decreased plasminogen activator inhibitor-1 (PAI-1) secretion from tumor cells and increased tumor fibrosis." (PMID 36497375, 2022). "The bioinformatics study revealed that ACSL3 mRNA expression was considerably lower in ccRCC tumor tissues than in renal tissues retrieved from the TCGA, GEO, and GEPIA databases." (PMID 36338658, 2022). "While the mechanisms by which fatty acid metabolism contribute to ccRCC tumor biology remain elusive, the clear role for ACSL3 in driving lipid droplet deposition and maintaining ccRCC viability highlights the potential of targeting this pathway." (PMID 36192773, 2022). "Having established that ACSL3 function is important for ccRCC cell line viability in vitro, we next sought to determine if ACSL3 was also important for ccRCC tumor biology in an in vivo model." (PMID 36192773, 2022). "Our findings revealed that certain FRGs (CISD1, ATP5MC3, PGD, SLC7A11, ACSL3, and FANCD2) are significantly upregulated in LUAD and that their elevated expression is associated with both advanced tumor stage and unfavorable prognosis." (PMID 35320929, 2021). "Together, these data suggest that ACSL3 supports the progression to PDAC by enhancing both tumor and stromal cell proliferation." (PMID 33127675, 2020). "In our study, ACSL3 overexpression increased proliferation, migration, and invasion of tumor cells, which favors malignancy." (PMID 33030783, 2020). "To better understand the mechanism leading to decreased tumor formation upon Acsl3 deletion, we evaluated tumor cell proliferation by Ki67 staining." (PMID 33127675, 2020). "We found that Acsl3 deletion reduced the percentage of Ki67+ cells in both tumor cells (Ki67+/cytokeratin+) and tumor stromal fibroblasts (Ki67+/αSMA+)." (PMID 33127675, 2020). "Our results show that Acsl3 is mainly expressed in tumor cells, suggesting that the reduction of tumor fibrosis and immunosuppression in Acsl3 knockout mice is specifically due to Acsl3 deletion in tumor cells." (PMID 33127675, 2020). "One key enzyme, acyl-coenzyme A synthetase long-chain family member 3 (ACSL3), facilitates the activation and incorporation of monounsaturated fatty acids into the cell membrane, and its expression is upregulated in disseminated tumor cells (DTCs)." (PMID 40977686, 2025). "ACSL3 promotes tumor progression by enhancing cellular energy metabolism." (PMID 41288931, 2025). "Additionally, ACSL3 promotes tumor cell apoptosis by downregulating phosphorylated YES proto-oncogene (pYES1), reducing nuclear localization of YAP, and decreasing B-cell lymphoma-extra large (BCL-xL) expression." (PMID 41288931, 2025). "Tumor cells might dynamically regulate the expression of ACSL3 and ACSL4 to fulfill specific metabolic demands or adapt to environmental stressors." (PMID 39744125, 2024). "The data suggest that ACSL5 may exert a suppressive function in low-grade lung tumors, while ACSL3 may enhance tumor proliferation in high-grade tumors." (PMID 38539505, 2024). "ACSL5 may inhibit tumor proliferation in low-grade lung tumors, while ACSL3 may enhance proliferation in high-grade lung tumors." (PMID 38539505, 2024). "In comparison to ACAT1, it was affirmed that ACSL3 in tumor tissues was up‐regulated." (PMID 39323079, 2024).
tumor (continued). "For FAO, ACSL3 inhibition with enhanced MGF can inhibit tumor, metastasis, and angiogenesis." (PMID 38841622, 2024). "Overexpression of FAO enzymes, such as the rate-limiting enzyme carnitine palmitoyltransferase 1 and acyl-CoA synthetase long-chain 3 (ACSL3), has been found in numerous malignancies and has been correlated to tumor growth, especially in adverse environmental conditions, such as glucose deprivation." (PMID 36839759, 2023). "Recent studies indicated that ACSL3 was increased in tumor tissue compared with normal liver." (PMID 37540213, 2023). "ACSL3 regulates the accumulation of lipid droplets in ccRCC and is essential for tumor growth." (PMID 36192773, 2022). "ACSL3 is up-regulated in CRC tissues in comparison to the corresponding non-tumor control." (PMID 35414781, 2022). "Furthermore, some researchers have discovered that ACSL3 can mediate the activation of monounsaturated fatty acids and promote the function of oleic acid, thereby potently inhibiting ferroptosis of tumor cells." (PMID 35223835, 2022). "Based on our in vitro findings, we decided to test whether ACSL3 inhibition and autophagy blockade can cooperate in suppressing tumor formation in vivo." (PMID 34998392, 2022). "To assess whether ACSL3 has any significance in CRC patients, we detected the protein level of ACSL3 in 30 pairs of tumor and non-tumor specimens by immunohistochemistry (IHC)." (PMID 35414781, 2022). "In addition, the objective of this study was to demonstrate a connection between tumor immune cell infiltration and ACSL3 transcription in ccRCC." (PMID 36338658, 2022). "Analysis of gene expression, mutation, DNA methylation, and prognostic value in LUAD revealed CISD1, ATP5MC3, PGD, SLC7A11, ACSL3, and FANCD2 to be significantly upregulated in LUAD and elevated expression of these FRGs to be associated with advanced tumor stage and poor prognosis." (PMID 35320929, 2021). "It is tempting to speculate that ACSL3, due to its function on the activation of FAs, may contribute to augment the FA β‐oxidation capacity of the cells conferring an advantage to tumor cells." (PMID 33030783, 2020). "Notably, we found that a high ACSL3 H-score positively correlates with a higher tumor histological grade." (PMID 33127675, 2020). "Neither tumor ACSL3 nor ACSL5 expression were associated with clinical outcome (data not shown)." (PMID 39853696, 2025). "Moreover, we have confirmed that ACSL3 is required for tumor metastasis in vivo." (PMID 35414781, 2022). "Therefore, we speculate that ACSL3 might be utilized to predict the efficacy of immune-blocking treatment in tumor patients who are effective in immunotherapy monitoring." (PMID 36338658, 2022). "Indeed, we showed that inhibition of acyl-CoA synthetase long chain 3 (ACSL3), an enzyme that activates extracellularly-derived fatty acids by adding a CoA moiety, delayed tumor growth, suppressed fibrosis, and enhanced the activation and abundance of CD8+ T cells in KPC mice." (PMID 33672917, 2021). "Finally, CISD1, ATP5MC3, PGD, SLC7A11, ACSL3, and FANCD2 expression was confirmed to significantly correlate with tumor mutational burden (TMB), microsatellite instability (MSI), immune cell infiltration, cellular checkpoint dysfunction, and cancer sensitivity to drugs." (PMID 35320929, 2021). "Thus, in principle, pharmacologic targeting of the ACSL3-LPIAT1 axis may benefit patients to selectively target tumor-derived prostaglandin synthesis while sparing normal cellular functions." (PMID 32034305, 2020). "Thus, we hypothesized that Acsl3 deletion could interfere with the cross-talk between tumor and stromal cells by affecting the secretion of soluble factors from tumors such as cytokines." (PMID 33127675, 2020). "Moreover, the H-score of ACSL3 (which takes into consideration the staining intensity in conjunction with the percentage of positive cells) appears overall reduced, with the ACSL3 levels being inversely proportional to the tumor stage." (PMID 31344914, 2019).